MS4A6E (membrane spanning 4-domains A6E)
Description:
May be involved in signal transduction as a component of a multimeric receptor complex.
Tractability: Antibody: UniProt predicts a signal peptide or a membrane-spanning region; its Gene Ontology location is reachable by antibodies, with medium confidence.
Gene: Protein-coding gene on chromosome 11 (60,327,251 to 60,396,596, forward strand). Ensembl gene ENSG00000166926.
Subcellular location: Membrane
Subcellular location (Human Protein Atlas): Vesicles
Gene Ontology:
Molecular function: protein binding
Biological process: cell surface receptor signaling pathway
Cellular component: plasma membrane; trans-Golgi network; membrane
Genetic constraint (gnomAD): Loss-of-function variants: 8 observed, 13.71 expected, observed/expected ratio (o/e) 0.58, 90% interval 0.34 to 1.05. The upper end of that interval is the gene's LOEUF score, 1.05, which puts it in group 4 of 6, group 1 being the genes least tolerant of losing a copy. Missense variants: 177 observed, 179.76 expected, observed/expected ratio (o/e) 0.98, 90% interval 0.87 to 1.12. Synonymous variants: 72 observed, 71.37 expected, observed/expected ratio (o/e) 1.01, 90% interval 0.83 to 1.23.
Homologues: Orthologues: chimpanzee MS4A6E (97% identical), macaque MS4A6E (77% identical), mouse Ms4a6d (52% identical), rat Ms4a6a (49% identical), rat Ms4a6b (46% identical), mouse Ms4a6b (45% identical), rat Ms4a6bl1 (42% identical), mouse Ms4a6c (41% identical), rat Ms4a6bl1 (41% identical), zebrafish ms4a17a.11 (21% identical), zebrafish ms4a17a.10 (20% identical), zebrafish ms4a17a.6 (20% identical), and 22 more. Paralogues in human: MS4A6A (80% identical), MS4A7 (31% identical), MS4A3 (21% identical), MS4A12 (20% identical), MS4A15 (20% identical), MS4A4A (20% identical), MS4A4E (20% identical), MS4A5 (19% identical), MS4A10 (18% identical), MS4A1 (17% identical), MS4A18 (17% identical), MS4A8 (17% identical), and 4 more.
Diseases named in the same sentence as MS4A6E in open-access papers:
MS4A6E is named in the same sentence as 2 diseases in open-access papers, as found by Europe PMC text mining. Sharing a sentence is not in itself a finding about the gene and the disease. The quoted sentences say what the papers report.
Alzheimer disease (3 papers, 2017 to 2025). A progressive, neurodegenerative disease characterized by loss of function and death of nerve cells in several areas of the brain leading to loss of cognitive function such as memory and language. "Other genes found to be associated with an increased risk of Alzheimer’s disease in a large genome-wide study are those coding three proteins from the MS4A family (membrane-spanning 4-domains), namely MS4A4A, MS4A4E, and MS4A6E." (PMID 40869138, 2025). "Although the precise role of MS4A4A, MS4A4E, and MS4A6E in Alzheimer’s disease is still under investigation, current evidence suggests that genetic variations in these proteins may affect immune function and microglial activity in the brain—key elements in the development of Alzheimer’s." (PMID 40869138, 2025). "We have shown an association between changes in gene expression in naïve and induced CD14+ monocytes and Alzheimer’s disease in seven genes in known Alzheimer’s disease loci, three of which (PVR, PTK2B and MS4A6E) replicated in TWAS using independent summary statistics." (PMID 33959712, 2021).
MS4A6E also shares sentences with these, for which no sentence is quoted: oligospermia (1 paper).